IFNB1 (interferon beta 1)
Diseases named in the same sentence as IFNB1 in open-access papers (continued):
Sharing a sentence is not in itself a finding about the gene and the disease.
infection (continued). "The constitutive RIG-I distribution across cells, and the parameters of IFNB1 induction were taken such that only the small number of cells with large amounts of RIG-I protein responded to infection." (PMID 21347441, 2011). "Half-maximal DDX58 expression occurred approximately 3 hours after infection, while half-maximal IFNB1 expression occurred 4–5 hours later." (PMID 21347441, 2011). "The time course for synthesis of the NDV L gene at 0, 3, 6, and 10 hours post infection showed significant NDV genome replication well before the half-maximal expression level of IFNB1 was reached." (PMID 21347441, 2011). "Indeed, aside from several cytokine genes, the large majority of canonical antiviral genes (most notably IFNB1 and ISGs) remained quiescent throughout the entire course of infection." (PMID 39869630, 2025). "Also, the authors determined that increased Ifnb1 mRNA expression in epithelial cells and IFN-β levels in bronchoalveolar lavage (BAL) of epTGF-βKO mice can be detected early after infection." (PMID 40431705, 2025). "Notably, activated MG 1 was the primary cell type expressing genes encoding RIG-I (Ddx58) and MDA5 (Ifih1), PRRs important in alphavirus sensing, along with type I IFN genes Ifnb1 and Ifna2 throughout infection." (PMID 39749347, 2024). "However, NFkB binding to both the MIEP and the IFNB1 promoter was reduced upon infection of an AD169-derivative that re-expresses UL138." (PMID 38932169, 2024). "Notably, enhanced expression of TTP, which enables recruitment of GIGYF1 to Ifnb1 mRNA, has been observed upon infection with several types of viruses." (PMID 39018414, 2024). "Additionally, our findings revealed that GUGG treatment significantly increased IFNB1 production in Huh7 cells following infection with various RNA viruses, such as EMCV, H1N1, and SEV." (PMID 39220861, 2024). "Compared with infected cells treated with the siRNA Control (siControl), IEC4.1 cells transfected with siPOOLs to CSpV1-dsRNAs following infection showed a decreased level of CSpV1-RdRp level with a similar infection burden but a significant inhibition on C. parvum-induced Ifnb1 expression." (PMID 36928642, 2023). "The results demonstrated that the levels of Ifnb1 transcripts in the liver and IFNβ in the blood in the Sting KO mice were much less than those in wild-type mice at both 4 and 7 weeks post infection, indicating that STING is required for the induction of IFNβ during S. japonicum infection." (PMID 35108342, 2022). "Consequently, PRV-∆UL13 infection enhanced the induction of IFNB1 and downstream ISGs, as well as the key inflammatory mediators, including IL6 and TNF." (PMID 35891444, 2022). "Consistent with the observation from the siRNA knockdown or sgRNA knockout of PRMT9, infection of Prmt9CKO peritoneal macrophages with SeV or stimulation with 5’PPP RNA led to a significant increase in the expression of Ifnb1, Ifnα4, and Cxcl10 mRNA compared with that in Prmt9WT macrophages." (PMID 36028484, 2022). "Resistance to infection and Ifnb1 induction depended on STING in both genotypes." (PMID 35588451, 2022). "However, only VACV∆C7L infection induced Ifnb1 gene expression, indicating that C7 is a negative regulator of the cytosolic dsRNA-sensing pathway." (PMID 35351885, 2022). "While infection with either virus triggered robust transcriptional interferon responses, including induction of type I (IFNB1) and type III (IFNL1) interferons, markedly lower levels of interferons and inflammatory proteins (IL-6, IL-8) were released following SARS-CoV-2 compared to H1N1 infection." (PMID 35840680, 2022). "Overexpression of Flag‐METTL14 decreased IFNB1 mRNA level upon infection with VSV." (PMID 34047074, 2021). "Similarly, overexpression of M markedly suppressed the SARS-CoV-2-induced transcription of IFNB1 and downstream antiviral genes at 6 and 24 h post infection in HEK293 cells stably expressing ACE2 (HEK293-ACE2)." (PMID 33110251, 2021).
infection (continued). "Significant IFNB1 upregulation was observed at 3 days post-infection." (PMID 34104087, 2021). "This led us to measuring Ifnb1 transcription at 16 h post-infection (or post-stimulation with KLA) in various IMM cell lines to determine the relative importance of TRIF, MAVS, and STING to the production of IFNβ at this critical stage following bacterial challenge." (PMID 33684179, 2021). "Infected BMDMs from C57BL/6 mice also showed decreased Ifnb1 expression upon MHV-A59 infection." (PMID 34479991, 2021). "Additionally, Ifnb1 transcript was again induced during cytosolic infection, where Il1b expression was induced during PAM-treatment alone, as well as during infection with wild-type or Δhly L. monocytogenes." (PMID 34555127, 2021). "Similarly, TSPOAP1-AS1 (translocator protein-associated protein 1-antisense 1), induced by IAV and p(I:C), accumulates in the nucleus after infection, inhibiting IFNB1 transcription and ISG expression, effectively helping viral replication." (PMID 32899429, 2020). "timepoint for subsequent experiments because this was when levels of both Ifnb1 and Ifna4 mRNA were at their highest following infection without causing overt suffering to the animal, allowing us to investigate the initial innate immune response." (PMID 31076606, 2019). "In addition, some eRNAs can continue to be transcribed beyond 12 h post-infection, as in the case for the IFNB1 and L2 and many other EP pairs." (PMID 30352805, 2018). "The Ifnb1 mRNA expression was modestly decreased in knockout cDCs at 12 h after infection." (PMID 29899553, 2018). "Despite vastly interfering with the Jak-Stat signaling, rabies infection could not decrease the expression of the famous antiviral molecule, IFNB1, and cell could have upregulated it against the infection." (PMID 27872612, 2016). "Interestingly, a more rapid decline of the IFNB1 mRNA level is observed at 48 hours post-infection compared to IFIT1 and TNF mRNA levels, which remained higher at this time point." (PMID 23785285, 2013). "Previous single cell measurements of IFNB1 induction in NDV infected human monocyte-derived dendritic cells (MDDCs) showed large cell-to-cell variation ranging over 3–4 orders of magnitude at 8–10 hours after infection." (PMID 21347441, 2011). "Six genes belonging to the two most significantly over-represented biological processes at the 15 min post H37Rv-infection ‘Immune system response’ (Ifnb1, Il12b, Ccl24, Pparg, and Clec4a2) and ‘Response to stimulus’ (Il13ra1) were selected for verification by RT-QPCR analysis." (PMID 22039457, 2011). "Thus far, integration of quantitative data on Ifnb1 (IFNβ gene) and ISGs expression in single cells over time and stochastic modeling allowed to demonstrate that paracrine signaling has a major impact on heterogeneous cell responses to infection." (PMID 37669278, 2023). "To investigate whether cGAS affects the type I interferon response during S. japonicum infection, we measured the mRNA levels of Ifnb1 in liver tissues and IFNβ in peripheral blood from wild-type mice and Cgas knockout (KO) mice at 4 and 7 weeks post-infection, respectively." (PMID 35108342, 2022). "However, the expression of IFNB1 quickly decreased to the baseline level at 7 days post-infection." (PMID 34104087, 2021). "However, the upregulation of Ifnb1 was not suppressed upon UBA3 deficiency although it was slightly reduced at 4 h post-infection upon MLN4924 pretreatment." (PMID 34506605, 2021). "Moreover, Ifnb1 was the only IFN gene consistently detected in our cellular model after infection." (PMID 29748576, 2018). "Additionally, we observed increases in the expression of EIF2AK2 (24-fold), OAS1 (10-fold), IFNA4 (10-fold) and IFNB1 (10-fold) in the lungs of rWSN-GH-NS1-Y84F infected mice treated with IFN-β on day 1 post-infection compared with the lungs of infected, but untreated mice." (PMID 28498306, 2017).
infection (continued). "In similar experiments, the induction of IFNB1 mRNA and the phosphorylation of TBK1 following infection with another DNA virus, HSV-1 (F-strain), were significantly increased." (PMID 40237449, 2025). "IP-10, IFNL1, IFNB1, and CASP1 gene expressions were significantly induced by Delta infection, whereas Remdesivir treatment prevented it efficiently with levels similar to non-infected cultures." (PMID 40142465, 2025). "Within the first two days of infection with either filovirus, ERB bmMΦs upregulated an identical cluster of type I IFN genes, including IFNB1, two IFNA-like, an IFNA4-like and an IFNW1-like gene – a response mirrored in SeV-infected cells." (PMID 41181097, 2025). "In normal human bronchial epithelial cells (NHBE), the Sendai virus triggered a rapid and robust expression of multiple antiviral genes with a peak at 6 h post-infection (hpi) with the fold of increase ranging from ~15,000 (for ISG15) to 800,000 (for IFNB1)." (PMID 40298378, 2025). "Silencing of SLAMF1 or TLR4 had minimal impact on HMPV-induced IFNB1 mRNA expression, except for a reduction observed in SLAMF1-silenced MDMs at 20 h post-infection." (PMID 41346628, 2025). "IFNB1 and IFIT1 transcription, as well as EMCV RNA replication, were quantified by RT-qPCR 7 h after infection." (PMID 40450684, 2025). "We compared TOA regimens (full, pre, co, post), evaluated combinations with nirmatrelvir (NL63) or GS-441524 (OC43) using ZIP scores, and profiled infection-context transcripts (IL6, IFNB1, ISG15, NRF2/antioxidant, UPR)." (PMID 41304814, 2025). "Consistently, knockdown of PCGF3 increased the expression levels of ISGs (ISG15, IFIT1, OAS2, MX1 and IRF7) and IFNB1, and decreased the VSV replicates (RNA level and virus titer) after VSV infection." (PMID 39368978, 2024). "The upregulation of Ifnb1 follows a similar trend as viral RNA, with lower levels for LGTV compared to TBEV at 24 h post-infection and a roughly 4-fold increase in levels between 24 and 72 h post-LGTV infection." (PMID 39205301, 2024). "After infection with HSV-1, cGAMP and exogenous nucleic acid stimulations, lower Ifnb1 and Il6 mRNA expression was found in the Ufl1−/− peritoneal macrophages." (PMID 35871231, 2023). "The RNA levels of many type I IFN genes, including Ifna13, Ifna7, Ifna1/5/6, Ifna1/2/5, Ifna4, Ifnab, Ifna12, and Ifnb1, were significantly increased in IEC4.1 cells 24 h post-infection." (PMID 36928642, 2023). "Our results demonstrate that while mRNA levels of Ceacam1 remained unchanged among groups, those mice supplemented with vitamin D exhibited elevated expression of Ifnb1, Isg15, and Isg20 following MHV-3 infection." (PMID 38140675, 2023). "Quantitative PCR (qPCR) analysis showed that PTK2B knockdown significantly attenuated the transcriptional levels of antiviral genes such as IFNB1, IFIT1 and CXCL10 induced by HSV1-GFP infection or by transfection with human telomeric DNA (HT-DNA)." (PMID 37989995, 2023). "Compared with the cells transduced with control shRNA, PRV-induced transcription of Ifnb1, Mx1, and Isg56 was increased in UL13-knockdown cells in different periods post-infection, suggesting that knockdown of UL13 enhances PRV-triggered antiviral responses." (PMID 35584187, 2022). "We confirmed a MDA5/STING-dependent upregulation of cytokine and chemokine genes after VACV∆C7L infection in AECII cells, including Ifnb1, Ccl2, Ccl7, Ccl4, Ccl5, and Cxcl10." (PMID 35351885, 2022). "We performed qRT-PCR to compare the mRNA levels of IFNB1 between RUNX1-knockdown and control cells after PR8 infection." (PMID 35248104, 2022). "qPCR experiments indicated that poly(dA:dT)-induced transcription of IFNB1, IL6, and TNFA genes was impaired by pre-infection with ASFV, suggesting that ASFV has evolved strategies to antagonize the Pol-III-RIG-I axis." (PMID 35089988, 2022).
infection (continued). "However, since rapamycin elevated viral ORF1A by 400-fold but only increased cellular IL6 and IFNB1 by 2.5-fold or less, these results suggest that rapamycin increased cellular susceptibility to SARS-CoV-2 infection, while limiting inflammatory cytokine induction in response to infection." (PMID 36264642, 2022). "Similar to infection in lung alveolar macrophages, MVA∆C7L induced higher levels of Ifnb1 gene expression in BMDCs compared with MVA." (PMID 35351885, 2022). "To this extent, we analyzed lung homogenates for the expression of Ccl2 and Ifnb1, and compared the data from co-infected mice to GAS mono-infection or uninfected controls." (PMID 36365071, 2022). "Consistently, the gene expression of Ifnb1, Il6, Cxcl10, and many ISGs was also reduced in BX795-pretreated cells during infection." (PMID 35604097, 2022). "Here, we corroborate these findings in Calu-3 cells using an unbiased genome-wide methodology showing that antiviral cytokines (IFNL1-3, IFNB1, CCL5, CXCL11 and IL6) are restricted in translation at 24 h post infection." (PMID 33806254, 2021). "(F) RT-PCR analysis of IFNB1, IFIT2, IFIT1, TNF, IL6, and CCL20 mRNA levels in HEK293T cells transfected with HA-Ev or HA-RTN3 followed by infection with VSV-eGFP (MOI = 1) at the indicated timepoints." (PMID 34313226, 2021). "Further RT-PCR analyses determined that the levels of IFNB1, IFIT2, IFIT1, TNF and the proinflammatory cytokines CCL20 and IL6 were enhanced by RTN3 knockdown during VSV infection, while the amplification of VSV was compromised." (PMID 34313226, 2021). "Gene expression of IFNB1, TNF, and IL-10 was measured 24 h following infection with Mtb H37RV at MOI of one." (PMID 33240287, 2020). "We found that overexpression of TRIM35 in THP-1 cells significantly enhanced transcription of IFNB1, TNFα, IL6, and ISG56 after infection with SeV." (PMID 32562145, 2020). "High expression levels of IL29 and low IFNB1 expression upon RIG-I and TLR3 activation in our cell line correlates with in vivo findings where HCV-infection of chimpanzees primarily induced the expression of type III IFNs." (PMID 32481600, 2020). "IE1cc172-176 expression resulted in significantly reduced induction of transcripts from the IFNB1, IFNL1, CCL5 and TNF genes relative to the wild-type protein following infection." (PMID 32365141, 2020). "The expression of IFNB1, ISG15, and IFIT1 mRNA were decreased in HEK293 cells transfected with Parkin upon infection with SeV." (PMID 32983119, 2020). "Only at high levels of IRF3 activity, i.e., at the peak of activity later in infection or brought about by expression of the constitutively active IRF3-S396D, p50-p65 is dispensable for IFNB1 transcription." (PMID 32645843, 2020). "IFNB1 (IFNβ gene) was also significantly and strongly induced by WNVKUN infection consistent with PRR pathway activation." (PMID 31664929, 2019). "Consistently, mRNA levels of IFNB1, ISG56, CXCL10, and IL6 genes induced by HCMV-ΔUL42 were significantly higher than those induced by HCMV-WT at 6, 12, and 24 hr post-infection in HFFs, human primary monocyte-derived dendritic cells and macrophages." (PMID 31107917, 2019). "In agreement with the IFNB1 findings, silencing of PSMB1 promoted the mRNA expression levels of TNFA and CCL5 after infection with IAV and VSV." (PMID 30682859, 2019). "The levels of Ifnb1 mRNA expression in liver, lung, and spleen of lnc-EPAV+/− mice were decreased after infection." (PMID 31363026, 2019). "Infection also results in enhanced expression of several IFN stimulated genes, especially IFNA1, IFNB1, and TLR3 transcripts." (PMID 31474994, 2019). "We observed approximately 0.5 to 1-log fold greater expression of ISG15, EIF2AK2, OAS1, IFNA4, and IFNB1 in the lungs of rWSN-GH-NS1-Y84F infected mice on days 1 and 3 post-infection compared with the lungs of rWSN-GH-NS1-wt infected mice." (PMID 28498306, 2017).
infection (continued). "In contrast to the unchanged TNFα mRNA levels, a decrease in IFNB1 mRNA was observed, which correlates with the reduced SNRNP200 mRNA at 1 hour post-infection in MDM." (PMID 27454487, 2016). "Upon infection, SNRNP200 binds viral RNA and relocalizes into TBK1-containing cytoplasmic structures to promote IRF3 activation and IFNB1 production." (PMID 27454487, 2016). "Among the genes belonging to the IFN pathway, CXCL10, IFNB1, IL28A and IL29 were increased after 24 h of infection." (PMID 23723976, 2013). "Additionally, compared to AFG3L2-deficient cells, cells reconstituted with wild-type AFG3L2 but not the protease-inactive AFG3L2E575Q mutant inhibited SeV-induced transcription of IFNB1 and IFI44 genes at 8 h post-infection." (PMID 41599057, 2026). "To further validate these findings, we knocked down Usp8 in Usp8fl/fl mouse embryonic fibroblast (MEF) cells via infection with Cre lentivirus and found that the EMCV‐induced expression of Ifnb1 and Cxcl10 and the EMCV‐induced phosphorylation of TBK1 and IRF3 were significantly impaired." (PMID 40525588, 2025). "We found that, in addition to a broad induction of ISGs (for example, DTX3L, OAS3, RTP4, IRF7, MX2, IFIT3, IFIH1), only IFNB1 and, more robustly, IFNL1-like and IFNL3-like were induced in virus-infected organoids at 1 and 3 days after infection compared to the uninfected controls." (PMID 40399606, 2025). "However, following infection with HCMV, VPA treatment resulted in a dramatic increase in IFNB1 transcript levels." (PMID 38932169, 2024). "Indeed, VSVΔ51 infection induced a large cross-section of antiviral genes (IFITs, IFITMs, OASs, ISGs) and different pro-inflammatory cytokines and chemokines (CCL5, CXCL10, IFNB1) that were all downregulated by 4-OI treatment." (PMID 38750019, 2024). "The differences in ISG expression were not dependent on changes in IFN gene expression, as Ifnl3, Ifnb1, and Ifna12 were not vastly altered throughout the course of infection (days 1, 2, 3, or 5 p.i.)between WT and Ifnlr1–/– mice." (PMID 38973611, 2024). "We broadly confirmed a decrease in inflammatory genes, including Ccl1, Cxcl9, Tnf, and Ifnb1, among others, in infected Gsdmd−/− versus WT mice, while no baseline differences were observed in the absence of infection." (PMID 38553499, 2024). "Infection with VSV but not treatment with pan-IFN strongly induced IFNB1 expression in all rhesus macaque kidney cell lines analyzed and induction efficiency was roughly comparable to that measured for A549 cells." (PMID 37146034, 2023). "Data on gene-fold change for IFNB1, CCL5, CXCL11, CXCL10, and IDO1 after experimental infection of HLMVEC by pathogenic (ANDV, HTNV) and nonpathogenic (PHV) viruses were recorded at seven timepoints t = 0, 12, 24, 36, 48, 60, 72 hpi." (PMID 37766212, 2023). "We conclude that IFNA1, IRF3, CXCL8, CXCL10, IFNB1, and CHUK are the key hub genes involved in the H5N1 human infection, which makes a major contribution towards the inflammation or cytokine storm leading to the prognosis of the disease and critical clinical outcomes." (PMID 37515084, 2023). "We observed a NS1 dosage-dependent host response for genes involved in the inflammatory response (IL-6, IFNB1) and interferon stimulation (IFIT1, MX1, ISG15), with the IAV-NS1-T infection generating an intermediate phenotype at both the transcript and at the protein levels." (PMID 37876781, 2023). "As expected, the absence of M35 resulted in a higher increase of Ifnb1 and Ifna4 transcription early after infection." (PMID 37289084, 2023). "We did not detect any IFNB1+ cells upon 5xSunTag-EMCV(LWT) infection, indicative of the potent antagonism exerted by the L protein and illustrating the benefit of using EMCV(LZn) mutant virus and IFIT1 as a reporter gene in studying antiviral responses." (PMID 37814072, 2023).